FAM20C (FAM20C golgi associated secretory pathway kinase)
Diseases named in the same sentence as FAM20C in open-access papers (continued):
Sharing a sentence is not in itself a finding about the gene and the disease.
small cell lung carcinoma (1 paper, 2024). Small cell lung cancer (SCLC) is a highly aggressive malignant neoplasm, accounting for 10-15% of lung cancer cases, characterized byrapid growth, and early metastasis. "Interestingly, copy number gains involving this genomic region known to harbor oncogenes such as UNCX, FAM20C, MAD1L1 and PDGFA have been reported during the immortalization process of patient-derived small cell lung cancer lines." (PMID 39737401, 2024).
Stroke (1 paper, 2023). Sudden impairment of blood flow to a part of the brain due to occlusion or rupture of an artery to the brain. "AZ_628, which screened from CMap analysis, was found to have lower binding energy with Mmp12, Lgals3, Fam20c, Capg, Pkm2, Sdc4, and Itga5 in microglia subcluster 2 and maybe a therapeutic agent for the poor development of microglia subcluster 2 after stroke." (PMID 38067435, 2023).
urothelial carcinoma (1 paper, 2024). A malignant neoplasm derived from the transitional epithelium of the urinary tract (urinary bladder, ureter, urethra, or renal pelvis). "The results indicated that high FAM20C levels were indicative of poor survival in immunotherapy for bladder and urothelial carcinomas." (PMID 39216004, 2024).
Von Willebrand disease type 2 (1 paper, 2025). "Finally, a Likely Pathogenic variant, p.Ser1517Arg, was found in VWF (encoding von Willebrand factor), and has been reported in a patient with von Willebrand disease type 2 (OMIM #613554), underscoring the potential role of FAM20C in the coagulation pathway." (PMID 41301500, 2025).
cancer (22 papers, 2021 to 2026). A tumor composed of atypical neoplastic, often pleomorphic cells that invade other tissues. "In cancer context, FAM20C has been implicated in enhancing the metastasis of several human cancers, making it a potential therapeutic target." (PMID 39216004, 2024). "Here, we aimed to analyze the expression and prognostic value of Fam20C in pan-cancer and to gain insights into the association between Fam20C and immune infiltration." (PMID 33306121, 2021). "Our study showed that increased expression of Fam20C is linked to poor prognosis in multiple cancer types, and the infiltrating immune cells associated with Fam20C expression in TME." (PMID 33306121, 2021). "More importantly, a wide range of secreted proteins phosphorylated by Fam20C were found to be associated with different cancers." (PMID 34988120, 2021). "FAM20C has also been implicated in the progression of other cancers." (PMID 39790934, 2025). "Therefore, Fam20C might be a prognostic biomarker in pan-cancer and its expression is in association with immune infiltration in BLCA, LGG, and STAD." (PMID 33306121, 2021). "Numerous studies have demonstrated the involvement of FAM20C in cancer progression, highlighting its potential as a promising therapeutic target for the prevention and treatment of related cancers." (PMID 39790934, 2025). "3.CDH2 (a substrate of FAM20C) is one of the markers of EMT that is associated with invasion and metastasis of cancer cells." (PMID 39790934, 2025). "FAM20C phosphorylates most secreted proteins, which play important roles in multiple biological processes, including cancer progression, biomineralization, and lipid homeostasis." (PMID 39790934, 2025). "Prior work also showed that FAM20C phosphorylates plasma proteins, although these studies were conducted in vitro using conditioned media from cancer cell line models." (PMID 41148235, 2025). "Specifically, FAM20C targets the serine (Ser) residue of S-x-E/pS motif in its target proteins that play essential roles in cancer progression, biomineralization, endoplasmic reticulum (ER) homeostasis, and other processes." (PMID 39790934, 2025). "Recent studies have highlighted FAM20C involvement in tumorigenesis, suggesting its potential as both a biomarker and a therapeutic target across various cancers." (PMID 41301500, 2025). "Our findings revealed a novel role for FAM20C, diverging from its previously recognized functions in bone development and cancer progression." (PMID 39532808, 2024). "Taken together, these results underscore the promoting effect of FAM20C on cancer malignant progression and indicate a collaborative pattern between FAM20C and CAFs that warrants further exploration." (PMID 39216004, 2024). "The deletion of the PCSK9 gene, one of the FAM20C substrates, substantially attenuates cancer cell growth in mice." (PMID 36825005, 2023). "In this study, we systematically detected the expression level of Fam20C in different types of cancer in the TCGA database." (PMID 34970298, 2021). "Accordingly, accumulating evidence has been demonstrating that Fam20C has several links to many types of human diseases, such as RS, cancer, and others." (PMID 34988120, 2021). "In PrognoScan database (data source from GEO), we performed an analysis to identify the cancer types which were related to Fam20C expression." (PMID 33306121, 2021). "In summary, elevated Fam20C expression can impact prognostic value in pan-cancer and increase degree of immune infiltration." (PMID 33306121, 2021). "It is still unclear that what role Fam20C expression plays in the process of tumorigenesisor in pan-cancer." (PMID 33306121, 2021). "Recently, the role of Fam20C in tumorigenesis has been illuminated and widely reported, making it a possible biomarker and potentially therapeutic target for diverse cancers." (PMID 34988120, 2021).
cancer (continued). "Next, we will complement in vivo/in vitro experiments to achieve the mechanisms of Fam20C in different cancer types at the cellular and molecular levels." (PMID 33306121, 2021). "Although previous studies have reported that expression of Fam20C was related to two cancer types (BRCA and LUAD), the prognostic values of Fam20C has not been given enough attention." (PMID 33306121, 2021). "The expression levels of Fam20C mRNA across different cancers, between tumor and normal tissue, were analyzed in Oncomine and TIMER databases." (PMID 33306121, 2021). "Considering the important role of Fam20C in various diseases, especially its role in tumorigenesis, targeting Fam20C is a potential treatment for diseases including cancer in the future." (PMID 34988120, 2021). "In order to analyze the Fam20C expression levels among different cancer, we examined differential Fam20C expression across pan-cancer and their matched paracancer normal tissues of datasets from Oncomine and 32 cancer types of TCGA data from TIMER." (PMID 33306121, 2021). "In the present study, we comprehensively analyzed the expression of Fam20C and its correlation with prognostic value in pan-cancer via different databases, including Oncomine, TIMER (Tumor Immune Estimation Resource), PrognoScan, and Kaplan–Meier plotter." (PMID 33306121, 2021). "Moreover, MCODE-based clustering revealed that PIGK and FAM20C belong to the same protein-protein interaction module enriched in cancer-related pathways." (PMID 41399371, 2026). "Clinical relevance is validated by immunohistochemistry on tissue microarray, and in vitro assays were conducted to assess PIGK-mediated phenotypes, regulation of Family with sequence similarity 20-member C (FAM20C), taxane response, and cancer-associated fibroblast (CAF) formation." (PMID 41399371, 2026). "The mechanisms that FAM20C contributes to cancer progression have been widely reported." (PMID 39790934, 2025). "FAM20C is upregulated in triple‐negative breast cancer and may play a critical role in tumor invasion and metastasis, with Fam20C knockout cancer cells showing less malignant invasion." (PMID 39532808, 2024). "In addition, for phosphorylated proteins, depletion of Fam20c resulted in increasing enriched in epithelial to mesenchymal transition (EMT), which was consistent with our previous bioinformatic analysis of Fam20C in pan-cancer." (PMID 37370126, 2023). "Existing studies have found two kinds of FAM20C inhibitors for cancer." (PMID 36825005, 2023). "In total, nine inflammation and cancer-associated DEGs were selected to show their changed expression patterns, comprising four up-DEGs (ADM, FSTL3, SPDEF, and SPNS2) and five down-DEGs (TACSTD2, CCL2, EDIL3, FAM20C, and OLFML2A)." (PMID 37953789, 2023). "In this study, we found that Fam20C was overexpressed in a variety of cancers, including LGG." (PMID 34970298, 2021). "Therefore, a further comprehensive study is required to understand the functional regulation of OPN by FAM20C-mediated phosphorylation in cancer." (PMID 34572536, 2021). "Moreover, molecular subtyping of diseases, especially of cancers with aberrant expression of Fam20C, represents a future direction." (PMID 34988120, 2021). "Some attempts to design inhibitors of Fam20C for treating cancer, focused in TNBC, have emerged." (PMID 34988120, 2021). "Therefore, in this research, we aim to study Fam20C in pan-cancer in order to draw an outline of the role of Fam20C in tumors." (PMID 33306121, 2021). "However, Fam20C expression in cancer and a consensus on the definition of other vital aspects like tumor cells metastasis are lacking." (PMID 33306121, 2021). "We observed that Fam20C widely expressed across many cancers and may affect the prognosis of patients by interacting with infiltrating immune cells." (PMID 33306121, 2021). "FAM20C is widely expressed across many types of cancers compared with the adjacent normal tissues." (PMID 34572536, 2021).
cancer (continued). "Notably, another crucial part of the present study is that Fam20C expression is correlated with various immune infiltration levels in cancer, especially in BLCA, LGG, and STAD." (PMID 33306121, 2021). "Almost all the previous studies on Fam20C focused on its role in organogenesis, including the development of salivary glands, biomineralization, amelogenesis, etc., while few were involved in cancers." (PMID 33942849, 2021). "Consequently, we selected cancer types in which the elevated Fam20C was negatively related to the tumor purity in TIMER and was largely related to bad prognosis in GEPIA." (PMID 33306121, 2021). "Among them, there were five cancer types in which Fam20C was overexpressed." (PMID 34970298, 2021). "In general, the expression of Fam20C showed a detrimental role in pan-cancer." (PMID 33306121, 2021). "Accordingly, some small-molecule inhibitors of Fam20C have been reported in cancer." (PMID 34988120, 2021). "Similarly, when comparing the expression level of Fam20C in cancer tissues with that in neighboring normal tissues, we found a large variation across different kinds of cancers which indicated the different roles in different cancers." (PMID 34899842, 2021). "Similarly, higher mRNA levels of Fam20C gave a worse prognostic prediction in all cancers (OS: total number, 9499; HR, 1.2; logrank P, 1.4e-05; DFS: total number, 9499; HR, 1.2; logrank P, 2.9e-06)." (PMID 33306121, 2021). "However, the expression of Fam20C in cancer and its effects on other important aspects, such as tumor cell metastasis, still lack consensus." (PMID 34970298, 2021). "Whether the expression or function of Fam20C and their products affects cancer cell growth and migration in the clinical setting is an important topic for future studies." (PMID 33306121, 2021). "Therefore, the elevated Fam20C expression most likely resulted in the poor prognosis in many cancers by regulating immune cell infiltration and cancer cell metastasis." (PMID 33942849, 2021). "Combined with previous research, our results remind that it should be noted that Fam20C may play diverse roles in various cancers." (PMID 33306121, 2021). "It is speculated that FAM20C can affect more cancer progression through the tumor microenvironment." (PMID 39790934, 2025). "This variability could stem from differences in the functions of AURKA and its downstream targets in various tumor types, akin to other genes such as DKK1 and Fam20C, which exhibit varying prognostic implications in different cancer types within pan-cancer studies." (PMID 37965456, 2023). "Therefore, enhancement of cancer cells in adhesion and migration, which may be accompanied by EMT, could be an underlying regulatory mechanism associated with Fam20C and bad prognosis." (PMID 33306121, 2021). "In addition, they also proposed the potential mechanisms how the increased Fam20C expression played a detrimental role in tumor progression by suggesting that the up-regulated Fam20C level affected the infiltration of immune cells and the capability of cancer metastasis." (PMID 33942849, 2021). "However, it remains unclear whether Fam20C plays a role in cancers." (PMID 33306121, 2021). "According to the regulation efficacy data, the positive regulation of TRIM15 and NHERF1 by CREB1 was reversed from normal to cancer; the negative regulations of TCEAL2, RBPMS2 and FAM20C by CREB1 disappeared; and the negative regulation of FERMT2 was reversed from normal to cancer." (PMID 35421923, 2022). "C1S, FAM20C, KDELR2, and RCAN2 have rarely been reported in cancer." (PMID 33579282, 2021). "The role of Fam20C in cancer was observed in earlier studies but has not previously been dissected." (PMID 33306121, 2021).
tumor (15 papers, 2021 to 2026). "The authors found that FAM20C potentially regulates tumor-associated macrophage polarization by inducing Treg cell activation and T-cell exhaustion." (PMID 36825005, 2023). "Our results provide insights for further understanding the pathological role of Fam20C in promoting tumor growth and invasion and its potential value as a diagnostic and prognostic marker for LGG." (PMID 34970298, 2021). "They found that Fam20C potentially regulated tumor-associated macrophages (TAM) polarization by inducing Treg cell activation and T-cell exhaustion." (PMID 33942849, 2021). "FAM20C substrates are implicated in tumor progression and immunotherapy." (PMID 36825005, 2023). "High expression of Fam20C was associated with tumor progression." (PMID 34970298, 2021). "Therefore, the loss of multiple FAM20C substrate phosphorylation contributes to cell motility defects, and the inhibition of FAM20C may be a viable therapeutic approach to prevent tumor growth and metastasis." (PMID 36825005, 2023). "Aiming at the roles of FAM20C in the invasion and metastasis of BRC, some studies have discovered some potential anti-tumor agents targeting FAM20C." (PMID 39790934, 2025). "Further validation of FAM20A and FAM20C expression in tumor samples was performed through mRNA level analysis using the TCGA database." (PMID 38983866, 2024). "FAM20C expression is most evident in the leading edge and peritumor areas with a large number of neurons, but relatively low in the tumor core and tumors outside the brain parenchyma, consistent with the observations in spatial transcriptomic analysis." (PMID 36823172, 2023). "Another evidence of supporting the role of Fam20C in tumor migration, revealed that the Fam20C inhibitor (FL-1607) designed by structure-based molecular modeling had the effects of antitumor growth, inducing cell apoptosis and inhibiting cell migration." (PMID 33306121, 2021). "The phosphorylated substrate of Fam20C is related to tumor cell apoptosis and migration and can accelerate the process of tumor metastasis by activating matrix metalloproteinases (MMPs)." (PMID 34970298, 2021). "Focusing on the substrates of Fam20C, studies have shown that Fam20C not only regulates some biological processes, but also involved in tumor growth and metastasis." (PMID 33306121, 2021). "More importantly, many Fam20C substrates are related to tumor cell apoptosis and metastasis, including insulin-like growth factor binding proteins, osteopontin, and serine protease inhibitors." (PMID 34970298, 2021). "Additionally, FAM20C was significantly upregulated in tumor tissues compared with normal tissues (P < 1 × 10-3) and correlated with nodal metastasis (P = 4.53 × 10-3) and advanced overall stage (P = 5.04 × 10-3)." (PMID 41399371, 2026). "Also, tumor purity was negatively correlated with Fam20C expression in BLCA (R, −0.587; P, 1.33e-35), LGG (R, −0.129; P, 4.78e-03), and STAD (R, −0.108; P, 3.58e-02)." (PMID 33306121, 2021). "Fibronectin 1 (FN1) was identified to interact with Fam20C and promote tumor cell migration." (PMID 34988120, 2021). "The relevance for the upregulation of Fam20c in the tumor of PD-1cKO mice is unclear and may be related to the phosphorylation of cytokines such IL-6, a known a substrate of Fam20c." (PMID 34912335, 2021). "Whether Fam20C affects the DCs or macrophages and tumor metastasis need to be done for further studies." (PMID 33306121, 2021). "Furthermore, the Fam20C substrates were also found to be involved in tumor growth and metastasis, including the insulin-like growth factor binding proteins (IGFBPs), osteopontin (OPN), serine protease inhibitors (Serpins), and several extracellular proteases." (PMID 33306121, 2021). "More directly, we found the association between Fam20C and immune cells markers suggested Fam20C might regulate tumor immunology in BLCA, LGG, and STAD." (PMID 33306121, 2021).
tumor (continued). "Fam20C is a casein kinase enriched in the Golgi apparatus that modulates many downstream substrates through protein phosphorylation and plays an important role in the formation of the secretome of tumor cells." (PMID 34970298, 2021). "Finally, many Fam20C phosphorylated substrates are also related to tumor cell apoptosis and migration, including insulin-like growth factor binding proteins (IGFBPs), OPN, and serine protease inhibitors." (PMID 34988120, 2021). "Moreover, several FAM20C substrates such as insulin-like growth factor-binding proteins (IGFBPs), osteopontin (OPN), bone morphogenetic protein 4, fibronectin 1, and fetuin-A (Fet A) are associated with the apoptosis, invasion, and metastasis of tumor cells." (PMID 39790934, 2025). "Therefore, it is indicated that FAM20C may promote GBM progression by affecting the tumor microenvironment." (PMID 39790934, 2025). "While the exact mechanism of how FAM20C regulates the crosstalk between neurons and RG-like cells remains to be investigated, these results serve as a proof of concept that we can use spatial transcriptomics to uncover functional regulators within a specific tumor niche." (PMID 36823172, 2023). "Therefore, the tumor promotion effect of FAM20A may be accomplished through the activation of FAM20C." (PMID 36825005, 2023). "Therefore, we speculate that the expression of Fam20C may affect the survival of patients through promoting the progression of tumor cells." (PMID 34970298, 2021). "However, the utility of Fam20C as a potential tumor diagnostic and prognostic marker has not been fully elucidated." (PMID 34970298, 2021). "Given the overlap between the extracellular proteins in our proteomics data set with known FAM20C substrates, it is of interest to note that a new small-molecule inhibitor of FAM20C proved effective to inhibit MDA-MB-231 migration in vitro and tumor growth in mice." (PMID 36374169, 2023). "In addition, we found that the expression of Fam20C was negatively correlated with tumor purity of LUAD, and positively correlated with immune cells infiltration, which further verified the relationship between Fam20C expression and poor prognosis." (PMID 33306121, 2021). "However, it remains to be determined whether FAM20C-driven mechanisms under ER stress influence GPI-anchoring processes and PIGK function, particularly in the context of tumor biology." (PMID 41399371, 2026). "Besides, Fam20C expression has no obvious relation with tumor purity and infiltrating levels of B cells, CD8+ T cells, CD4+ T cells, macrophages, and neutrophils in DLBC, at the same time in GEPIA showed Fam20C played a protective role of prognosis in DLBC." (PMID 33306121, 2021).